LRRC14B (leucine rich repeat containing 14B)
Tractability: PROTAC: ubiquitination databases record sites on it.
Gene: Protein-coding gene on chromosome 5 (191,495 to 196,334, forward strand). Ensembl gene ENSG00000185028.
Subcellular location (Human Protein Atlas): Cytosol; Nucleoplasm
Genetic constraint (gnomAD): Loss-of-function variants: 25 observed, 15.29 expected, observed/expected ratio (o/e) 1.63, 90% interval 1.17 to 1.95. The synonymous counts are far from expectation, so gnomAD's model fits this gene poorly and the ratio says little. Missense variants: 766 observed, 636.62 expected, observed/expected ratio (o/e) 1.2, 90% interval 1.13 to 1.28. Synonymous variants: 358 observed, 298.37 expected, observed/expected ratio (o/e) 1.2, 90% interval 1.1 to 1.31.
Homologues: Orthologues: chimpanzee LRRC14B (99% identical), macaque LRRC14B (96% identical), rabbit LRRC14B (83% identical), pig LRRC14B (81% identical), dog LRRC14B (80% identical), guinea pig LRRC14B (80% identical), mouse Lrrc14b (80% identical), rat Lrrc14b (79% identical), tropical clawed frog lrrc14b (50% identical), zebrafish lrrc14b (44% identical). Paralogues in human: LRRC14 (29% identical), PRAME (23% identical), PRAMEF6 (21% identical), PRAMEF12 (21% identical), PRAMEF5 (21% identical), PRAMEF7 (21% identical), PRAMEF8 (21% identical), PRAMEF11 (20% identical), PRAMEF15 (20% identical), PRAMEF25 (20% identical), PRAMEF26 (20% identical), PRAMEF27 (20% identical), and 12 more.
Diseases named in the same sentence as LRRC14B in open-access papers:
LRRC14B is named in the same sentence as 8 diseases in open-access papers, as found by Europe PMC text mining. Sharing a sentence is not in itself a finding about the gene and the disease. The quoted sentences say what the papers report.
cardiac hypertrophy (1 paper, 2016). "Although little is directly known about its neighboring gene LRRC14B, the LRRC superfamily contains members which consist of one modulatory auxiliary subunit of BK channels, whose dysfunction can lead to disease in humans including high blood pressure and cardiac hypertrophy." (PMID 28040802, 2016).
LRRC14B also shares sentences with these, for which no sentence is quoted: cancer (1 paper); cardiac disease (1); glaucoma (1); high blood pressure (1); myotonic dystrophy type 1 (1); osteogenesis imperfecta (1); Treacher-Collins syndrome (1).